NPBWR1 (neuropeptides B and W receptor 1)
Description:
Interacts specifically with a number of opioid ligands. Receptor for neuropeptides B and W, which may be involved in neuroendocrine system regulation, food intake and the organization of other signals. Has a higher affinity for neuropeptide B.
Synonyms: GPR7
Tractability: Small molecule: a high-quality ligand is known; it belongs to a druggable protein family. Antibody: its Gene Ontology location is reachable by antibodies, with high confidence; UniProt places it where antibodies can reach, with medium confidence; UniProt predicts a signal peptide or a membrane-spanning region. PROTAC: a small molecule that binds it is known.
Target class: Peptide receptor (family A GPCR); Family A G protein-coupled receptor; Short peptide receptor (family A GPCR); Membrane receptor; Neuropeptide receptor
Chemical probes: CYM 50769, ML181
Gene: Protein-coding gene on chromosome 8 (52,939,182 to 52,943,734, forward strand). Ensembl gene ENSG00000288611.
Subcellular location: Cell membrane
Pathways (Reactome):
Signal Transduction: G alpha (i) signalling events; Peptide ligand-binding receptors
Gene Ontology:
Molecular function: protein binding; G protein-coupled opioid receptor activity; G protein-coupled receptor activity; neuropeptide binding; neuropeptide receptor activity
Biological process: G protein-coupled receptor signaling pathway; chemical synaptic transmission; neuropeptide signaling pathway; G protein-coupled opioid receptor signaling pathway
Cellular component: membrane; neuron projection; plasma membrane; synapse
Genetic constraint (gnomAD): Loss-of-function variants: 6 observed, 4.8 expected, observed/expected ratio (o/e) 1.25, 90% interval 0.66 to 1.89. That is too few expected variants to judge how well the gene tolerates losing a copy. Missense variants: 545 observed, 445.08 expected, observed/expected ratio (o/e) 1.22, 90% interval 1.14 to 1.31. Synonymous variants: 250 observed, 213.53 expected, observed/expected ratio (o/e) 1.17, 90% interval 1.05 to 1.3.
Homologues: Orthologues: chimpanzee NPBWR1 (100% identical), macaque NPBWR1 (98% identical), dog NPBWR1 (90% identical), pig NPBWR1 (89% identical), rat Npbwr1 (86% identical), mouse Npbwr1 (85% identical), rabbit NPBWR1 (83% identical), guinea pig NPBWR1 (76% identical), tropical clawed frog npbwr1 (64% identical), Caenorhabditis elegans trhr-1 (23% identical), Drosophila melanogaster Rh7 (23% identical). Paralogues in human: NPBWR2 (61% identical), SSTR3 (38% identical), OPRD1 (37% identical), SSTR1 (35% identical), SSTR5 (35% identical), OPRL1 (35% identical), SSTR4 (34% identical), SSTR2 (34% identical), OPRM1 (34% identical), OPRK1 (33% identical), KISS1R (30% identical), PTGDR2 (26% identical), and 5 more.
Diseases named in the same sentence as NPBWR1 in open-access papers:
NPBWR1 is named in the same sentence as 15 diseases in open-access papers, as found by Europe PMC text mining. Sharing a sentence is not in itself a finding about the gene and the disease. The quoted sentences say what the papers report.
Anxiety (6 papers, 2011 to 2025). Intense feelings of nervousness, tension, or panic often arise in response to interpersonal stresses. "The increased responses to various stresses in Npbwr1−/− mice suggest the possibility that these mice show high anxiety." (PMID 21390312, 2011). "Therefore, the fact that Npbwr1−/− mice showed such a specific phenotype in the light/dark exploration test and not in others might simply reflect the fact that these tests measure different dimensions of anxiety-related behaviors, such as impulsivity." (PMID 21390312, 2011). "We did not detect significant effects of virally altered Npbwr1 levels on anxiety in the open-field test." (PMID 39433904, 2025). "For instance, we do not exclude the possibility that Npbwr1 may regulate anxiety when manipulated in other brain regions such as the amygdala, or affect weight when manipulated in relevant brain regions such as the hypothalamus." (PMID 39433904, 2025). "Finally, the strong, discrete expression of NPBWR1 in the extended amygdala and abundant projections of NPW fibers in these regions suggest that this neuropeptide system has a role in the regulation of fear and anxiety." (PMID 23515889, 2013). "As Npbwr1−/− mice had normal thigmotaxis and a normal response in the elevated plus maze, this response to light-dark exploration might reflect increased impulsivity of Npbwr−/− mice to a novel physical environment rather than heightened anxiety." (PMID 21390312, 2011).
Obesity (3 papers, 2010 to 2021). Accumulation of substantial excess body fat. "Nevertheless, as we already mentioned, NPB or NPBWR1‐deficient mice have features consistent with adult‐onset obesity as well as impaired energy expenditure, which is a hallmark of brown fat tissue deficiency." (PMID 33629519, 2021). "For example, it was found that genetic depletion of NPBWR1 in male mice leads to adult‐onset obesity and impaired energy expenditure." (PMID 33629519, 2021). "It is important to note that the loss of brown adipocytes is accompanied by obesity and decreased energy expenditure, which resemble metabolic abnormalities descripted in NPB‐ or NPBWR1‐deficient mice." (PMID 33629519, 2021). "Consistent with the phenotype of Npbwr1−/− mice, Npb−/− mice were also reported to exhibit mild adult-onset obesity." (PMID 23515889, 2013). "Both Npb−/− and Npbwr1−/− mice show late-onset obesity and hyperphagia, suggesting that the endogenous NPB-NPBWR1 pathway negatively regulates feeding behavior and positively regulates energy expenditure." (PMID 23515889, 2013). "Furthermore, ob/ob;NPBWR1−/− and Ay/a;NPBWR1−/− double mutant male mice had an increased body weight compared with normal ob/ob or Ay/a male mice, suggesting that the obesity of NPBWR1−/− mice is independent of leptin and melanocortin signaling." (PMID 23515889, 2013).
prostate carcinoma (3 papers, 2020 to 2024). A carcinoma that arises from epithelial cells of the prostate gland. "And methylation of NPBWR1 is significantly associated with prostate cancer prognosis." (PMID 33552958, 2020). "Opioid receptors have been heavily linked to prostate cancer biology and some have been proposed as potential targets such as OPRK1 which hints at the possibility of NPBWR1 being able to be targeted in a similar way." (PMID 38983753, 2024). "NPBWR1, also known as GPR7, has been associated with prostate cancer prognosis, but its role in tumor development and its potential use as a therapeutic target has yet to be understood." (PMID 38983753, 2024). "Using prostate cancer as a case study, the best features were identified and utilized to train machine learning algorithms to predict 5 novel promising therapeutic targets for prostate cancer: IGF2R, C5AR, RAB7, SETD2 and NPBWR1." (PMID 38983753, 2024). "Using these similarities, we discovered that NPBWR1 was highly similar to two other proteins in the network, GNAI1 involved in prostate cancer growth and GNAI2 involved in prostate cancer cell migration and invasion." (PMID 38983753, 2024). "Indeed, NPBWR1 shares 96 % percent of its protein partners with both GNAI1 and GNAI2 (26 out of 27 protein interactions), revealing that they might act on similar molecular pathways within prostate cancer." (PMID 38983753, 2024).
depression (2 papers, 2023 to 2025). "In summary, these data further demonstrate a causal link between long-term changes in Npbwr1 and depression-associated symptoms." (PMID 39433904, 2025). "Using viral-mediated gene transfer, we identify a causal link between Npbwr1 and depression-related phenotypes." (PMID 39433904, 2025). "Consistently, the regulation of Npbwr1 activity via microinjection of ligands altered depression-related symptoms depending on a previous CVS induction." (PMID 39433904, 2025). "Npbwr1 is increased in the nucleus accumbens of chronically stressed mice and postmortem in patients diagnosed with depression." (PMID 39433904, 2025). "Several SNPs are described within the NPBWR1 gene, which are mostly of uncertain significance or have no known link to depression." (PMID 39433904, 2025). "NPBWR1 among serotonin genes and POLI in kynurenine pathway genes were significantly associated with depression in the low but not in the high TLR group." (PMID 36973313, 2023).
non-small cell lung carcinoma (2 papers, 2010 to 2016). A group of at least three distinct histological types of lung cancer, including non-small cell squamous cell carcinoma, adenocarcinoma, and large cell carcinoma. "In addition, Esteller and the associates used methylation array to establish methylation profiles of stage I Caucasian non-small cell lung cancer and identified that methylation of two or more genes in HIST1H4F, PCDHGB6, NPBWR1, ALX1, and HOXA9 correlated with an increased risk of cancer recurrence." (PMID 27484806, 2016).
schizophrenia (2 papers, 2021 to 2025). A major psychotic disorder characterized by abnormalities in the perception or expression of reality. "Interestingly, NPBWR1 is located in the 8q11.23 region, neighboring the RB1CC1 gene, and two NPBWR1 duplications are associated with schizophrenia, making this gene potentially interesting in yet another disease context." (PMID 39433904, 2025).
breast carcinoma (1 paper, 2020). "CCNE1, NPBWR1, A2ML1, EXO1 and TTK displayed good prognostic/diagnostic value for breast cancer and BRCA1/2-mutant breast cancer." (PMID 31998560, 2020). "In our study, we found that NPBWR1 and A2ML1 have certain prognostic or diagnostic significance for breast cancer, and we thought that the two molecules also deserve further investigated, though their expression level in breast cancer tissues is not high enough overall." (PMID 31998560, 2020). "Using the survival analysis, we found that CCNE1, NPBWR1, A2ML1 and TTK might act critical functions in the oncogenesis and progression of BRCA1/2-mutant breast cancer, reflected by their diagnostic efficacy for BRCA1/2 mutations and prognostic value as well." (PMID 31998560, 2020). "Although the NPBWR1, A2ML1 and C4orf51 displayed differential expression, their expression level in breast cancer tissues is still not high, which may be due to their own expression abundance or sensitivity of the detection probe." (PMID 31998560, 2020).
Diabetes (1 paper, 2022). "The change in the expression level of NPBWR1 in DRG neurons caused by diabetes suggests the involvement of this signaling system in the pathophysiology of diabetic sensory neuropathy." (PMID 36499546, 2022). "This could explain why the difference in the expression of NPBWR1 caused by diabetes was detected just in LV." (PMID 36499546, 2022). "Diabetes caused an increase in NPBWR1 mRNA expression but no protein expression difference was detected by the WB analysis." (PMID 36499546, 2022).
Hypertension (1 paper, 2021). The presence of chronic increased pressure in the systemic arterial system. "NPW increases the calcium flow into the cells by acting on NPBWR1 and plays a role in regulating vascular myofibrillar tension, so it may be involved in the development of hypertension." (PMID 34568491, 2021).
cancer (2 papers, 2016 to 2023). A tumor composed of atypical neoplastic, often pleomorphic cells that invade other tissues. "We also found a few novel lncRNAs such as LINC00940 and FLJ16779 that have not been reported earlier besides SNHG19, NPBWR1, and lncRNAs that are known to be involved in cancer and other diseases as well." (PMID 37218885, 2023).
tumor (2 papers, 2020 to 2024). "Among them, the UALCAN database showed that CXCL3 was related to the trait of histological types in ESCA and READ, GPR44 (PTGDR2) was associated with tumor grade in ESCA and NPBWR1 was related to patients’ age in ESCA and READ." (PMID 33552958, 2020). "Furthermore, Disease Meth version 2.0 analysis showed that the mean methylation levels of NPBWR1 was higher in tumor tissue than normal tissue both in ESCA and READ (P < 0.01)." (PMID 33552958, 2020). "The hub gene ADCY6, CXCL3, NPBWR1, TAS2R38, and PTGDR2 highly influence the clinical traits of age, histology types, neoplasm histologic grade, and overall survival in ESCA and READ, leading to their similarity in these clinical traits." (PMID 33552958, 2020).
NPBWR1 also shares sentences with these, for which no sentence is quoted: colon tumors (1 paper); mood disorder (1); neuroendocrine tumors (1); Onset (1).